BMP4 (bone morphogenetic protein 4)
Diseases named in the same sentence as BMP4 in open-access papers (continued):
Sharing a sentence is not in itself a finding about the gene and the disease.
cancer (180 papers, 2006 to 2025). A tumor composed of atypical neoplastic, often pleomorphic cells that invade other tissues. "First, we extracted the cancer cell subgroup and determined the DEGs associated with BMP4 dysregulations." (PMID 41169612, 2025). "Dysregulation of BMP4 is closely associated with cancer cell growth, apoptosis, migration, and invasion." (PMID 41169612, 2025). "Cancer associated fibroblasts (CAFs) upregulated TFAP2A expression by bone morphogenetic protein 4 (BMP4)." (PMID 40727938, 2025). "While ID1 was the most significantly upregulated in SMAD4-expressing tumors, it is a well-known target of BMP4 and has been implicated in the promotion of metastasis in different cancer types." (PMID 38689334, 2024). "ACSL4 upregulated by bone morphogenetic protein 4 (BMP4) enhances the cancer cell fatty acid metabolism, which is associated with acquired drug resistance in EGFR-mutant NSCLC cells." (PMID 38539505, 2024). "Studies have reported that BMP4 is implicated in the progression of many types of cancer, like breast, colon, bladder, and gastric cancer." (PMID 37370018, 2023). "BMP4 is associated with many aspects of carcinogenesis but has different effects on different cancer types." (PMID 36756161, 2023). "SHH is known to upregulate several types of BMPs including BMP4 and can be produced by cancer-associated fibroblasts in the cancer microenvironment." (PMID 35902550, 2022). "Patel A.K., Vipparthi K., Thatikonda V., Arun I., Bhattacharjee S.,Sharan R., Arun P., Singh S. A subtype of cancer-associated fibroblastswith lower expression of alpha-smooth muscle actin suppressesstemness through BMP4 in oral carcinoma." (PMID 35342854, 2022). "The most relevant cancer formation pathways, such as Wnt, BMP4, and TGFb, are associated with SCRGs." (PMID 34452555, 2021). "BMP4 contributes to various cancer-associated phenotypes, including cell growth, differentiation, migration, invasion, and angiogenesis, which is critical for cancer development and progression." (PMID 30079292, 2018). "Low-ATM levels are associated with increased BMP4 levels and elevated stem cell gene signatures, which have been previously linked to disease outcome in a variety of cancers including colorectal cancer." (PMID 26220524, 2015). "To further confirm that BMP-4 inhibits the expression of MMP-9, we used gremlin, a natural antagonist of BMP-4 which is highly expressed in cancer-associated stromal cells." (PMID 25897433, 2015). "BMP4 has also been implicated in the development of several cancers including HCC,33,34 a major cause of mortality in HCV-infected patients." (PMID 23775568, 2014). "Functional studies in multiple malignancies suggest that BMP4 typically causes reduced growth and increased migration of cancer cells." (PMID 24053318, 2013). "Both in vivo and in vitro studies have demonstrated the role of BMP4 on suppression of cell growth, induction to migration, invasion and epithelial-mesenchymal transition, which are associated with cancer metastasis and progression." (PMID 23590708, 2013). "Strikingly, activin A and BMP4 upregulated many growth factors, tyrosine kinase receptors (RTKs), and G protein-coupled receptors in both the cell lines, many of which are associated with the development of cancer." (PMID 37048077, 2023). "Besides, the upregulated BMP4 also has been reported to be associated with many cancers and negatively associated with overall survival." (PMID 37370018, 2023). "In some cancers, BMP4 was also reported to be associated with poor prognosis." (PMID 33452764, 2021). "For example, undergoing cancer education, normal tissue MSCs are inverted into cancer-associated MSCs and communicate with cancer cells via forming a positive feedback loop, BMP4:HH, to promote cancer growth and drug resistance and enrich them stem cell-like pool." (PMID 32377504, 2020).
cancer (continued). "The BMP4 signals from cancer-associated mesenchymal stem cells further activate expression of HH in cancer stem cells, and that action drives more BMP4 production from the mesenchymal cells, forming a positive feedback loop that confers resistance to chemotherapeutics." (PMID 30122445, 2018). "Furthermore, a previous study found that there is a BMP4-Hh-positive feedback loop between CSCs (cancer stem cells) of ovary cancer and CA-MACs (cancer-associated mesenchymal stem cells), which enhances the proliferation of CSCs." (PMID 28883837, 2017). "Therefore, BMP4 and its associated pathways may be used as a biological indicator for the development of various types of cancers, including HCC." (PMID 28947976, 2017). "Single-cell transcriptomic data further showed BMP4 expression in cancer cells and cancer stem cells." (PMID 41169612, 2025). "In contrast, by analyzing the relative expressions of BMP4 in various cell lines of different cancer types, we found that BMP4 was highly expressed in the cancers of the pancreas, eye, liver, etc.." (PMID 41169612, 2025). "As BMP4 was enriched in the cancer cells and CSCs, we extracted these two types of cells from the scRNA-seq data and studied the impacts of BMP4 level changes on the expressions of other genes, respectively." (PMID 41169612, 2025). "Pan-cancer analysis revealed distinct expression and prognostic patterns of BMP4, while pathway analyses indicated that BMP4 predominantly regulates metabolic rather than canonical BMP signaling." (PMID 41169612, 2025). "BMP2 and BMP4, particularly BMP4, present in various tissues, have been linked to the induction of EMT in cancer." (PMID 41013839, 2025). "Next, we analyzed the correlation between the expression and methylation of BMP4 in all cancer types." (PMID 41169612, 2025). "By equally dividing the cancer cells into two groups, high- and low-BMP4 cells, according to cell-intrinsic BMP4 expressions, we analyzed the DEGs using a built-in function, “FindMarkers”, in the “Seurat” package." (PMID 41169612, 2025). "Conversely, CAFs expressing low levels of α-SMA suppressed self-renewal and growth of stem-like cancer cells through the signalling molecule bone morphogenetic protein 4 (BMP4)." (PMID 39780187, 2025). "By integrating bulk and single-cell transcriptomic data, we revealed that BMP4 is enriched in cancer cells and CSCs, correlates with poor prognosis, and shows a distinctive role in regulating metabolism rather than canonical BMP signaling." (PMID 41169612, 2025). "Previous studies have reported upregulation of BMP4 in various cancer types, including melanoma, gastric, and ovarian cancers." (PMID 41169612, 2025). "In this study, we assessed BMP4 expression in pan-cancer tissues and their matched normal counterparts, with notable dysregulation in PAAD." (PMID 41169612, 2025). "Consistent with this, we retrieved the transcriptomic profile data of different cohorts of PAAD and found that the expressions of BMP4 were enriched in the malignant cancer cells, epithelial cells, and fibroblasts." (PMID 41169612, 2025). "We next investigated the prognostic values of BMP4 in all cancer types listed in the TCGA database, the outcomes of which were highly divergent according to different cancer types." (PMID 41169612, 2025). "As a result, we found that BMP4 was specifically enriched in CSCs and cancer cells, and was also clearly expressed in epithelial cells and fibroblasts." (PMID 41169612, 2025). "At the cellular level, BMP4 reduces the number and activity of myeloid-derived suppressor cells which have an immunosuppressive role in cancer." (PMID 39273106, 2024). "EMT induction is attributed to BMP2 and BMP4 in the realm of cancer, with BMP4 extensively engaged across diverse tissues." (PMID 38329598, 2024).
cancer (continued). "Bone Morphogenetic Protein 4 and oncolytic viral therapy further highlight the diverse approaches being explored to tackle this aggressive cancer, with research necessary to optimize these promising strategies." (PMID 39328617, 2024). "In conclusion, our study demonstrates that the anti-metastatic effect of BMP4 is mediated by SMAD4-dependent signalling that is transduced either in the cancer cells or in the stromal cells." (PMID 38689334, 2024). "In this study, we have re-analysed the transcriptomic data recovered from human cancer cells grown as xenografts in mice to characterise the impact of BMP4." (PMID 39273106, 2024). "BMP4 belongs to the transforming growth factor-beta family and has been shown to impact cell growth, differentiation, migration, and invasion in cancer cells." (PMID 38062093, 2023). "Accordingly, BMP4 can sensitize cancer cells to anoikis by regulating a variety of downstream genes involved in metastasis." (PMID 37090717, 2023). "Some of the high scoring BioChIP-seq enrichment sites included genes that have been implicated in cancer metastases (DDR1, BMP4, and SMAD6), and cell cycle and survival (CDIP1 and PPP2R5A)." (PMID 36207293, 2022). "Accordingly, in vitro treatment of TNBCs with BMP4 protein, resulted in a significant reduction in cancer stem cell populations." (PMID 36510219, 2022). "BMP2 and BMP4 (BMP2/4) are critically involved in malignant signaling leading to cancer progression and are well-known for their involvement in metastatic and invasive behavior of cancer." (PMID 35902550, 2022). "For instance, BMP4 has been observed to be correlated with tumorigenesis and resistance to anti-cancer treatment by affecting FA metabolism in lung cancer." (PMID 34249928, 2021). "Having shown that TGFβ inhibits BMP4 while promotes stemness, we next assessed the role and contribution of cyclin D1 in controlling cancer stem cell numbers." (PMID 33649296, 2021). "Altogether, these results indicate that the two family members, BMP4 and TGFβ, antagonize each other effect in the regulation of cancer stemness and highlight BMP4 as a potent pro-differentiation factor in TNBC." (PMID 33649296, 2021). "We further found TGFβ and BMP4 to antagonize each other effect on cancer stemness in high-grade, invasive basal-like tumors, and show that their relative expression (high TGFβ/low BMP4 levels) correlated with poor prognosis and survival outcomes." (PMID 33649296, 2021). "As a regulator of oxidative factors, BMP4 is upregulated under oxidative stress which will facilitate cancer progression." (PMID 33892661, 2021). "We show here that BMP4 acts as a potent differentiation factor and prevents cancer stemness by inhibiting tumorsphere formation and reducing CD44+/CD24− CSC numbers in TNBC." (PMID 33649296, 2021). "We further found that BMP4 opposed TGFβ effects on stemness and potently decreased cancer stem cell numbers, thereby acting as a differentiation factor in TNBC." (PMID 33649296, 2021). "BMP4 silencing partially inhibits TAZ-induced migration, suggesting that BMP4 signaling is one of the pathways engaged by TAZ to confer migratory properties to cancer cells." (PMID 34439395, 2021). "The upregulated BMP4 is also able to reciprocally stimulate ROS pathway and act on cancer progression." (PMID 33892661, 2021). "In the mouse testicular embryonal carcinoma cell line, RA induces Bmp2 while simultaneously repressing Bmp4, specifically through RARα and RARγ." (PMID 34292881, 2021). "Regarding the function of BMP4 in cancers, BMP4 has been indicated to mediate the differentiation of cancer stem cells and inhibit the cancer growth of CRC." (PMID 32149326, 2020).
cancer (continued). "Based on our findings, BMP4 was significantly correlated with age, histological differentiation, and cancer stage (P = 0.004, 0.044, and 0.019, respectively)." (PMID 32201526, 2020). "It further revealed that chromatin accessibility at gene promoters is necessary but not sufficient for productive gene expression, which has been reported in other systems such as response to BMP4 signaling in cancer." (PMID 32553182, 2020). "Given that only some cancers express high levels of gremlin and noggin we sought to investigate their inhibitory effects on both BMP4 and BMP7v." (PMID 31591478, 2020). "In a murine model of OSCC, a sub-population of CAFs, characterized by low α-SMA expression and secretion of bone morphogenetic protein 4 (BMP4), was reported to decrease cell proliferation and inhibit cancer stem cells." (PMID 33114328, 2020). "This antagonistic activity of BMP signaling against stem cells and Wnt pathway seems preserved in the cancer counterpart as indicated by the ability of BMP4 to promote differentiation and apoptosis of CR-CSCs." (PMID 31591478, 2020). "Collectively, these data suggest that BMP-4 enhances the cancer stem cell traits of MDA-MB-231 cells via Notch signaling." (PMID 31409851, 2019). "Since BMP-4 increased the expression of cancer stem cell markers in MDA-MB-231 cells, we also carried out both mammosphere and colony formation assays." (PMID 31409851, 2019). "We focused on the BMP pathway as BMP2 and BMP4 regulate SC fate, maintenance and differentiation processes and contribute to cancer SC emergence, maintenance and expansion." (PMID 30262802, 2018). "These BMP4-related effects that seem either detrimental (reduced cell growth) or beneficial (increased mobility) for the cancer cells are likely to be mediated by specific BMP4 target genes." (PMID 28077088, 2017). "In previous studies, BMP4 was found play important roles in developmental and many cellular processes including invasion and migration of various cancer cells." (PMID 28231844, 2017). "GATA6 is also reported to participate in cancer cell invasion and metastasis by regulating other proteins, such as urokinase plasminogen activator, slug and BMP4." (PMID 28270130, 2017). "Previous studies have also shown that BMP4 can induce EMT in human cancer cells and that SMAD1 participates in the BMP4-induced EMT process." (PMID 27027434, 2016). "In various cancers, BMP4 has been found to induce epithelial-mesenchymal transition (EMT) but its function in the development of EAC is currently unclear." (PMID 27191723, 2016). "For example, while we know that BMPs can increase MMP expression in some cancer cells, such as gastric or prostate cancer cells, others have shown that BMP-4 treatment of C3HT101/2 stem cells blocks MMP-3 and MMP-13 expression." (PMID 25897433, 2015). "Based on these findings, we concluded that BMP4 is one of the key downstream factors that mediate miR-200’s effects on lung tumorigenesis and metastasis and is a candidate target for directed cancer therapy." (PMID 26395571, 2015). "BMP4 has been reported to exert inhibitory or stimulatory functions during cancer initiation and metastasis, depending on the tissue and cancer type." (PMID 26395571, 2015). "Previously, in a hepatitis B virus X antigen-induced HCC mouse model, we identified genes that were significantly up-regulated at the pre-cancer and cancer stages, including Edn1, Src, Bmp4, and Bmp7." (PMID 24416389, 2014). "Although the basic function of BMP4 is to induce bone formation, it is reported to play a role in the development and metastasis of malignant tumors." (PMID 24099560, 2013).
cancer (continued). "Their key regulatory subunit, the bone morphogenetic protein 4 (BMP4), is overexpressed and associated with pathogenesis and metastasis in a variety of cancers." (PMID 23590708, 2013). "We believe the data in this article provides a foundation for further evaluation of BMP-4 in the context of VACV replication in combination with other treatments in cancer indications such as GBM in the clinic in the near future." (PMID 23800258, 2013). "A heterogeneity in BMP4 expression depending on disease type, from benign disease to malignant tumors, has been observed." (PMID 24099560, 2013). "Further evidence for excluding a role of BMP-4-mediated growth inhibition in differentiated cells in the context of VACV infection came from testing more differentiated cancer cell lines grown in the presence of serum." (PMID 23800258, 2013). "In recent years, important new advances has been generated on the contribution of BMP family members, such as BMP4, in cancer pathogenesis." (PMID 23590708, 2013). "Considering its effects on growth suppression, BMP4 has been suggested as a possible therapeutic target in cancer cells." (PMID 23590708, 2013). "BMP4 expression in cancer varies and both increased and decreased expression has been reported depending on the tissue of origin." (PMID 24053318, 2013). "Similar to BMP4, these DEGs were also enriched in the cancer cells and CSCs." (PMID 41169612, 2025). "Consistently, BMP4 was also discovered to be expressed in CSCs and cancer cells." (PMID 41169612, 2025). "Subsequently, we explored the prognostic values of BMP4 methylation in all cancer types." (PMID 41169612, 2025). "In this study, we have sought to understand the reason for the conflicting reports of the impact of BMP4 on progression of different types of cancer, especially in cancers of the gastrointestinal tract or the pancreas where cancer promoting activities of BMP4 were identified." (PMID 38689334, 2024). "In NT2/D1 cells, both activin A and BMP4 treatments significantly altered Hippo signalling pathway, an important pathway that controls cell growth and differentiation, often dysregulated in a number human cancers." (PMID 37048077, 2023). "TNF was significantly hypomethylated in 15 cancers, IL6 was significantly hypomethylated in 14 cancers, and BMP4 was significantly hypermethylated in 12 cancers, indicating that these important genes were regarded in a stably consistent manner among different types of cancer." (PMID 36945884, 2023). "Epithelial-mesenchymal transition (EMT) as one of the most important mechanisms in cancer metastasis also has been reported by many studies that could be induced by BMP4 in many kinds of cancer." (PMID 37370018, 2023). "The critical role of BMP4 in cancer pathogenesis has been reported." (PMID 36756161, 2023). "Furthermore, CAFs with lower α-SMA expression can promote cell proliferation but inhibit the self-renewal of oral stem-like cancer cells through bone morphogenetic protein 4 (BMP4)." (PMID 36244987, 2022). "BMP-4 expression is upregulated in cancer-associated fibroblasts (CAFs) in HCC tissues compared to non-cancerous liver fibroblasts." (PMID 35693928, 2022). "The essential role of BMP4 in erythroid cell development and its ability to regulate vital processes, such as angiogenesis and hematopoiesis have made this signaling molecule an increasingly interesting topic in cancer research." (PMID 35694408, 2022). "The abnormal expression of BMP4 has been confirmed in various cancers, including NSCLC." (PMID 35021154, 2022). "Whether the later stage tumors that continue to express higher levels of BMP4 are growing faster or slower is unknown but an increase in expression of this protein may be an early indicator of carcinoma." (PMID 36612143, 2022). "BMP4 is also a member of the TGFβ superfamily, thus suggesting the existence of a negative feedback loop between TGFβ family members to regulate the balance between cancer stemness and differentiation." (PMID 33649296, 2021).